SOD3 (superoxide dismutase 3)
Diseases named in the same sentence as SOD3 in open-access papers (continued):
Sharing a sentence is not in itself a finding about the gene and the disease.
lung carcinoma (continued). "This may suggest that the response of peripheral lung cancer may be stronger if SOD3 is used as a therapeutic target." (PMID 35356201, 2022). "In lung cancer tissues, the expression of SOD3 was found to be remarkably reduced (P = 4.218e-29)." (PMID 35356201, 2022). "This may suggest that the high expression of SOD3 affects the prognosis of patients with lung cancer, making cancer cells difficult to be cleared by anti-cancer drugs." (PMID 35356201, 2022). "Additionally, restoring SOD3 in tumor endothelial cells has been shown to normalize tumor vasculature and improve tissue perfusion, thereby enhancing the efficacy of doxorubicin in lung cancer mouse models." (PMID 41028519, 2025). "In this study, we explored the role of SOD3 gene in the prognosis and immune-related therapy of lung cancer, and made consumption that low expression of SOD3 gene in patients may lead to increased sensitivity of tumor to chemotherapy drugs, resulting in better prognosis." (PMID 35356201, 2022). "We believed that the occurrence and growth might be promoted by SOD3 in lung cancer." (PMID 35356201, 2022). "SOD3 and SOD1P3 regulate active oxygen in the microenvironment and are downregulated in lung cancer." (PMID 38791918, 2024). "The SOD3 high expression set and the low expression set were compared by GSEA to determine the signal pathways activated in lung cancer." (PMID 35356201, 2022). "The down-regulation of SOD3 stage III and IV lung cancer expression was also explained." (PMID 35356201, 2022). "Therefore, for lung cancer patients, cancer cells with high expression of SOD3 gene may not be insensitive to chemotherapy and other regiments, so the treatment effect is not good." (PMID 35356201, 2022).
pancreatic cancer (10 papers, 2017 to 2024). "Recently, it was discovered that deficiency in EcSOD or SOD3 is involved in metastasis of multiple cancer types including TNBC and pancreatic cancer." (PMID 30941174, 2019). "In contrast, it has been shown that SOD3 overexpression leads to suppression of the hypoxic accumulation of HIF-1ɑ in human pancreatic cancer cells, with a concomitant decrease in VEGF levels." (PMID 29707113, 2018). "Moreover, we detected AgNP-induced disturbance of antioxidant system (SOD1, SOD2, GPX-4, CAT, and SOD3) in pancreatic cancer cells." (PMID 30186549, 2018). "SOD2 expression is higher than SOD1, SOD3, and CAT in pancreatic cancers." (PMID 37891871, 2023).
psoriasis (10 papers, 2013 to 2025). An autoimmune condition characterized by red, well-delineated plaques with silvery scales that are usually on the extensor surfaces and scalp. "Overexpression of SOD3 found to ameliorate several auto-immune diseases such as arthritis, psoriasis and the alternation in the level of SOD3 found to be associated in inflammatory bowel diseases and systemic lupus erythematosus." (PMID 33717151, 2021). "For example, enhanced therapeutic efficacy on psoriasis mouse model was achieved when MSCs over-expressed SOD3." (PMID 36433947, 2022). "SOD3-overexpressing MSCs specifically prevented the development of psoriasis in a mouse model of imiquimod (IMQ)-induced psoriasis-like inflammation via the inhibition of the TLR7/MAPKs/NF-κB axis and the activation of the adenosine receptor." (PMID 33805942, 2021). "Recently, SOD3-transduced MSCs showed increased therapeutic potential of MSCs than normal MSCs alone in imiquimod-induced psoriasis-like skin inflammation mouse model." (PMID 32128111, 2020). "Similarly, SOD3 also showed to ameliorate chronic skin dermatoses such as psoriasis, atopic dermatitis, and acne." (PMID 32128111, 2020). "Similar to the observation in psoriasis-like inflammation mouse model, SOD3-transduced MSCs exhibited reduced ROS levels, recruitment of inflammatory cells with suppressed expression of inflammatory mediators compared with normal MSCs in mice with AD-like skin inflammation." (PMID 32128111, 2020). "Therefore the role of SOD3 in the skin is unclear although it has been shown that SOD3 is involved in skin inflammation and its expression is reduced in psoriasis." (PMID 25906193, 2015). "Also, SOD3 expression is reduced in psoriasis patients compared to healthy subjects, further supporting this." (PMID 23624605, 2013). "By contrast, SOD3 KO mice display exaggerated IL23-mediated psoriasis-like skin inflammation, including increased immune cell infiltration and higher levels of pro-inflammatory cytokines compared to WT controls, suggesting a role for SOD3 in cutaneous inflammation." (PMID 23624605, 2013). "In our previous study, we proposed that direct administration of SOD3 protein, as well as MSC-delivered SOD3 can exert efficient therapeutic efficacy against allergic dermatitis, allergic airway inflammation, and psoriasis-like skin inflammation." (PMID 34208517, 2021). "SOD3 also found to suppress TLR-7-induced downstream NF-κB, and JAK-STAT signaling pathway in imiquimod-induced psoriasis-like skin inflammation mouse model." (PMID 32128111, 2020).
colorectal cancer (9 papers, 2018 to 2025). A primary or metastatic malignant neoplasm that affects the colon or rectum. "Upregulating SOD3 reduces tumor development and liver metastases in colorectal cancer, indicating that SOD3 may have diagnostic and prognostic implications for the treatment of colorectal cancer." (PMID 40867576, 2025). "In contrast, exosomal superoxide dismutase-3 (SOD3) imparted resistance to lipid peroxidation in colorectal carcinoma cells." (PMID 40977891, 2025). "In a pre-clinical model of colorectal cancer, it was demonstrated that up-regulation of superoxide dismutase 3 (SOD3) enhances tumor infiltration by CD8+ T cells by activating WNT pathway in the ECM." (PMID 33466303, 2021). "In primary colorectal cancers, it was found a significant correlation between enhanced SOD3 mRNA levels, stromal HIF-2α stabilization and VEC expression, suggesting that this SOD3-HIF-2α pathway also stabilizes the AJ in the vasculature of human tumors." (PMID 33250894, 2020). "SOD3 also regulates TIL density in primary human colorectal cancers (CRC), thus affecting the relapse rate and patient survival." (PMID 33250894, 2020). "Importantly, these SOD3-induced changes were also associated with the increased infiltration of cytotoxic CD8+ T cells and prolonged disease-free survival in patients with colorectal cancer." (PMID 35267534, 2022). "This SOD3/HIF-2α/LAMA4 pathway is operative in human primary colorectal cancer (CRC)." (PMID 33250894, 2020). "The present review focuses on SOD3 since two recent reports have shown that the cancer-driven repression of this anti-oxidant enzyme is related to tumor vessel abnormalization and T-cell exclusion in both experimental and primary colorectal cancers." (PMID 33250894, 2020). "Finally, future studies should incorporate the distinct roles of different SOD isoforms (SOD1, SOD2, and SOD3) in colorectal cancer prognosis, as their specific contributions may influence biomarker development and clinical applications." (PMID 41479776, 2025). "SOD3, VEC, and HIF-2α levels correlated positively in primary colorectal cancers, which suggests a similar interconnection of these proteins in human malignancy." (PMID 29422508, 2018). "Superoxide dismutase 3 has been shown to be related to the regulation of HIF-1α, which participates in the process of several malignancies, such as breast, lung, pancreatic, and colorectal carcinomas." (PMID 39234408, 2024). "We next measured SOD3 and VEC mRNA levels in freshly frozen samples from a cohort of 102 colorectal carcinoma (CRC) patients (stages I–IV) and in non-tumor samples >10 cm from the primary tumor in the same patients." (PMID 29422508, 2018).
emphysema (9 papers, 2012 to 2024). "Our obtained results on SOD expression are in line with previous findings in COPD pathology, as a decrease of SOD3 has been related to emphysema." (PMID 39014439, 2024). "The experiments on murine lungs showcased that the presence of SOD3 restricts the development of emphysema and reduces the breakdown of the extracellular matrix due to oxidative stress in the murine lung." (PMID 38585534, 2023). "SOD3 maintains NO bioavailability and protects against several lung disorders, including oxidative injury, emphysema, inflammation, and fibrosis." (PMID 30574096, 2018). "In a murine model of emphysema, the mice that overexpress the sod3 gene or are treated with a SOD mimetic have improved lung compliance, decreased neutrophil influx, release of proinflammatory mediators, and oxidative damage." (PMID 26266917, 2014). "The percentual treatment effect in both inflammation models was comparable with the effect previously obtained with transgenic SOD3 overexpression in pulmonary emphysema." (PMID 22529530, 2012). "Positive modulation of SOD3, either in SOD3-transgenic mice or via administration of the pharmacological SOD-mimetic MnTE-2-PyP to WT or SD3-KO mice, attenuated features of emphysema and reduced oxidative fragmentation of the ECM in mouse lungs." (PMID 36978796, 2023). "Consequently, the researchers concluded that the pharmacological activation of SOD3 within the pulmonary system might serve as a therapeutic intervention for managing COPD and emphysema." (PMID 38585534, 2023).
Insulin resistance (9 papers, 2011 to 2024). Increased resistance towards insulin, that is, diminished effectiveness of insulin in reducing blood glucose levels. "A small preliminary study of the Ala40Thr polymorphism of the superoxide dismutase 3 gene (SOD3), which has been associated with insulin resistance, reported a significant excess of the mutant allele in women with severe intrauterine growth restriction." (PMID 21429808, 2011). "Furthermore, participants with insulin resistance displayed a higher GSH/GSSH ratio and higher activity of SOD-3, indicating the compensatory response started to counteract the chronic oxidative stress overload." (PMID 36358463, 2022).
thyroid cancer (9 papers, 2012 to 2025). "SOD3-derived PTC MSCs have been shown to support thyroid cancer cell proliferation and inhibit cancer cell migration." (PMID 36077709, 2022). "Ca2+ signaling was shown to regulate SOD3 expression as the GPCR-PLC-Ca2+ signaling pathway increases SOD3 mRNA expression to stimulate thyroid cancer cell proliferation." (PMID 29478325, 2019). "Although the expression of the enzyme is gradually downregulated in thyroid cancers and thyroid cancer cell lines, a recent article demonstrated increased SOD3 mRNA synthesis in PTC MSCs, therefore suggesting an autocrine/paracrine switch in SOD3 production." (PMID 29478325, 2019). "In the current work, we studied the mechanisms regulating SOD3 expression in vitro using thyroid cell models representing different stages of thyroid cancer." (PMID 26550576, 2015). "Importantly, SOD3 expression in stromal cells has been shown to modulate cancer cell growth and migration in thyroid cancer." (PMID 41028519, 2025). "Previous studies have demonstrated downregulation of ROS-producing extracellular superoxide dismutase (SOD3) in thyroid cancer cell lines although according to recent data, the expression of SOD3 at physiological levels stimulates normal and cancer cell proliferation." (PMID 28216675, 2017). "Increased SOD3 expression in tumor stroma MSCs stimulated thyroid cancer cell proliferation but decreased cancer cell migration, indicating that SOD3 may reduce the intratumoral affinity of cancer cells and allows them to migrate locally toward peritumoral regions." (PMID 29478325, 2019). "Additionally, SOD3 has been reported to be downregulated in thyroid cancer tumors." (PMID 22529530, 2012). "In thyroid cancer, for instance, mesenchymal stem/stromal cells (MSCs) isolated from papillary thyroid carcinoma (PTC) exhibit higher SOD3 expression than MSCs from benign thyroid tissues." (PMID 41028519, 2025). "Thus, the identification of SOD3-coordinated signal transduction in tumor stroma and epithelial cancer cells may reveal small drug target molecules that could be used in combination therapy for the treatment of thyroid cancer." (PMID 28216675, 2017). "As a conclusion, according to our data PC Cl3, PC PTC1, PC E1A cell model systems corresponded to human NOX2, NOX4, SOD3, CATALASE, GPX5, and GPX7 gene expressions in thyroid cancer." (PMID 26664298, 2015). "For example, stromal SOD3 had a stimulatory effect on thyroid cancer cell growth and an inhibitory effect on cancer cell migration, POSTN expression was activated by ΔNp73 and modulated epithelial-mesenchymal transition of thyroid cancer cells." (PMID 36973751, 2023). "The average Log2 median-centered intensity-normalized SOD2 expression in the normal thyroid is markedly lower, −0.34, than that of SOD1 and SOD3 but different from these two because SOD2 expression gradually increases, correlating with the malignancy of thyroid cancer." (PMID 29478325, 2019).
type 2 diabetes (9 papers, 2015 to 2025). "Interestingly, the T-allele of rs2284659 in the promoter region of SOD3 has been related to a safer plasma redox balance, leading to an improvement in the cardiovascular outcome in patients with type 2 diabetes." (PMID 35883714, 2022).
heart failure (7 papers, 2015 to 2025). Inability of the heart to pump blood at an adequate rate to meet tissue metabolic requirements. "The diminished expression of the antioxidant superoxide dismutase-3 (SOD3) is linked to an elevated risk of heart failure in diabetic patients." (PMID 38824159, 2024). "Studies demonstrated that decreased SOD3 levels are linked to elevated ROS levels in the aortas of older rats, while upregulated expression of SOD3 enhanced endothelial function in hypertensive and heart failure rat models." (PMID 40700116, 2025). "We tested the hypothesis that diabetic subjects heterozygous for extracellular superoxide dismutase (SOD3) R213G, which entails lower antioxidant capacity in tissues, have increased risk of cardiovascular disease and heart failure." (PMID 26844281, 2015). "Taken together, it seems biologically plausible that the SOD3 R213G variant, by drastically reducing tissue affinity of the SOD3 enzyme and leaving the vascular tissue with low protection against superoxide radicals, may increase the risk of cardiovascular disease and heart failure." (PMID 26844281, 2015). "Thus, in the present study we tested the hypothesis that diabetic subjects heterozygous for the SOD3 R213G genetic variation, which entails lower antioxidant capacity in tissues, have increased risk of cardiovascular disease and heart failure." (PMID 26844281, 2015). "Our results find further support in the decreased levels of antioxidant SOD3 and increased expression of MMP9, both established markers of heart failure." (PMID 38824159, 2024). "Our results suggested that PECGGp may suppress unbalanced oxidant and antioxidant status in infarcted myocardium, coronary arteries damage, atherosclerotic plaque, and heart failure development by inhibiting levels of MDA and elevating NO, eNOS, and SOD3 levels." (PMID 28044093, 2016).
ischemic stroke (7 papers, 2018 to 2025). A stroke disorder caused by obstruction of blood flow to the brain, due to thrombotic (local blood clot formation) or embolic (due to a blood clot or other material traveling from another site) event. "The SNP rs7655372 in the SOD3 gene was associated with an increased risk of ischemic stroke, and the SNP rs17880487 in the SOD1 gene was associated with an increased risk of cardiovascular mortality." (PMID 36875474, 2023). "These are consistent with our results, demonstrating that the SOD3 is effective in ameliorating the damage caused by ischemic stroke." (PMID 31461803, 2019). "Increased SOD3 is also associated with reduced BBB damage, smaller infarct volumes, and improved neurological outcomes following ischemic stroke." (PMID 40362325, 2025). "SOD3 is an extracellular antioxidant enzyme that protects against ischemic stroke by scavenging ROS produced during ischemia–reperfusion injury." (PMID 40362325, 2025). "In a previous study, six single-nucleotide polymorphisms (SNPs) within SOD genes were investigated to determine their association with ischemic stroke: rs17880487 and rs80265967 in SOD1, rs4880 and rs2842960 in SOD2, and rs2695232 and rs7655372 in SOD3." (PMID 36875474, 2023). "In our study, with the ischemic rat model of SOD3‐MSCs transplantation, the volume of cerebral infarction was significantly reduced, and the neurological function was significantly restored, indicating that the SOD3 has therapeutic effects on ischemic stroke." (PMID 31461803, 2019). "In this study, we examine the efficacy of PNA, an extracellular superoxide dismutase (EcSOD or SOD3) mimetic that was originally developed for ischemic stroke." (PMID 30941174, 2019). "It is speculated that overexpression of SOD3 affects the expression of Bax and Bcl‐2, and improves apoptosis to alleviate ischemic stroke." (PMID 31461803, 2019). "Therefore, the purpose of this study was investigating the effect of SOD3 transfection with MSCs on ischemic stroke." (PMID 31461803, 2019). "In this experiment, we preliminarily speculated on the role of SOD3 transfection of MSCs in the treatment of ischemic stroke." (PMID 31461803, 2019). "It was reported that LIF could protect neurons by upregulating the superoxide dismutase 3 after ischemic stroke." (PMID 29896414, 2018). "Although the effect of MSCs on ischemic stroke in rats has been studied, the effect of MSCs cells transfected with SOD3 on ischemic stroke has not been reported until now." (PMID 31461803, 2019).
prostate carcinoma (7 papers, 2017 to 2025). A carcinoma that arises from epithelial cells of the prostate gland. "Certain SOD3 gene variants are linked to an increased risk of cancers, such as cervical and prostate cancers." (PMID 40558258, 2025). "There is less prostate cancer invasion when SOD3 is overexpressed, or the expression of the cysteine/glutamate transporter is decreased." (PMID 34943029, 2021). "The superoxide dismutase (SOD) family consists of SOD1, SOD2, and SOD3 proteins that neutralize the first oxygen-derived ROS and provide protection against the development of cancers, including prostate cancer." (PMID 34943029, 2021). "Prostate cancer with a high Gleason score has a higher cysteine/glutamate transport expression and lower SOD3 expression." (PMID 34943029, 2021). "Similarly, Overexpression of SOD3 acts as a tumor suppressor in PC-3 prostate cancer." (PMID 33717151, 2021). "In that study, the level of SOD3 expression was not influenced by the grade of the prostate cancer." (PMID 34943029, 2021).